MYC (MYC proto-oncogene, bHLH transcription factor)
Diseases named in the same sentence as MYC in open-access papers (continued):
Sharing a sentence is not in itself a finding about the gene and the disease.
lymphoma (continued). "In developing lymphoma cells, this corruption might reflect pre-GC mutations of CREBBP, while in our screen this oncogenic corruption could be provided by the forced expression of BCL2, BCL6, or MYC." (PMID 31586074, 2019). "Indeed, we recently showed that in HL and ALCL, MYC is a direct target of BATF3, so that the promotion of constitutive expression of this proto-oncogene is presumably a main pathogenic function of BATF3 in these lymphomas." (PMID 29662618, 2018). "Thus, the c-MYC inhibitor may be a suitable substance for reducing the number of viable lymphoma cells." (PMID 28724379, 2017). "This very interesting study suggests that IGH/MYC-induced BRCA2 deficiency may predispose Burkitt lymhpoma cells to synthetic lethality triggered by PARP1 inhibitors, which might of course also be relevant for other lymphoma types with similar activation of MYC." (PMID 29057015, 2017). "Although the deregulation of MYC alone could probably be overridden by cellular “defense” mechanisms, leading to apoptosis of the affected cell, aberrant MYC signaling in lymphomas is accompanied by changes in additional key regulatory pathways that are usually involved in apoptosis." (PMID 28375188, 2017). "However, MYC/BCL6 DHLs or MYC/BCL2/BCL6 “triple-hit” lymphomas can also occur." (PMID 27606052, 2016). "MIZ1-mediated repression is required for tumor formation in MYC-driven lymphoma and medulloblastoma, suggesting that targeting the complex may provide a second strategy with a significant therapeutic window for MYC-dependent tumors." (PMID 27460974, 2016). "However, other lymphomas with MYC and BCL2 rearrangements have received less attention." (PMID 26517511, 2015). "Melanoma and MYC-driven lymphoma cells exhibit high levels of replication stress and show excellent sensitivity to Chk1 inhibitors in vitro, suggesting that these cancer types might be suitable candidates for testing the efficacy of single agent treatment in vivo." (PMID 26295265, 2015). "Because MYC deregulation can occur via different modes, we hypothesized that in distinct lymphoma phenotypes, high-level MYC expression may come under the controls of different transcriptional and epigenetic regulatory mechanisms, which may be sensitive or resistant to JQ1/Brd4 inhibition." (PMID 24466310, 2014). "In addition, restimulation of splenocytes from lymphoma surviving mice with a murine fibrosarcoma cell line, stably transfected to express human c-MYC (MCA205MYC-tet), also resulted in a significantly higher IFNγ secretion compared to untransfected MCA205 cells." (PMID 24130880, 2013). "Since MYC is regarded as an important oncogene in several types of malignant lymphomas (including BL), this new observation might be of high relevance for the understanding of the biology of these lymphomas." (PMID 22102868, 2011). "To determine whether miRNAs associated with malignancy could be detected in the peripheral blood, we used real-time reverse transcriptase-PCR to determine miRNA profiles in whole blood obtained from transgenic mice with c-MYC-induced lymphoma, hepatocellular carcinoma and osteosarcoma." (PMID 18826639, 2008). "In lymphoma diagnostics, particularly for DLBCL and HGBCL, a Hi-C-based lymphoma assay enables diagnosis-agnostic detection of gene fusions of IGH::MYC and IGH::BCL2, and rearrangements of MYC, BCL2, and BCL6, in a single assay." (PMID 41010038, 2025). "DEL is different from “double-hit lymphoma” (DHL), which refers to lymphoma with BCL2, MYC or BCL6 gene rearrangements, but DEL is also predictive of tumors with high metabolic activity, inhibition of apoptosis, and risk of treatment resistance." (PMID 41229502, 2025). "In MYC-driven lymphomas, KTN1-AS1—directly transactivated by MYC—co-regulates MYC-target genes while co-activating cholesterol synthesis effectors, such as SQLE." (PMID 40722703, 2025).
lymphoma (continued). "Specifically, certain BCL6 FISH probes can misinterpret a single MYC rearrangement as dual oncogenic events by detecting both BCL6 promoter and MYC-BCL6 enhancer rearrangements, thereby inflating triple-hit lymphoma rates." (PMID 41364305, 2025). "CDCA7 stabilizes MYC protein through AKT-mediated phosphorylation, thereby inhibiting the expression of pro-apoptotic factors such as Bim and promoting lymphoma cell transformation." (PMID 41189944, 2025). "A biopsy of the tumour mass (Case‐07‐HGBCL) showed a transformed lymphoma with the large cell component being BCL2+ (50%), TdT+ (60%), MYC+ (80%)." (PMID 41047873, 2025). "High-grade B-cell lymphomas with MYC and BCL-2 and/or BCL-6 rearrangements occur in 5% to 10% of DLBCL cases, commonly referred to as double- or triple-hit lymphomas." (PMID 41445799, 2025). "In summary, our results demonstrate that STAT3, MYC, and EBNA1 collaborate to regulate the expression of ZC3H18, a protein that is upregulated in EBV+ lymphomas." (PMID 40354417, 2025). "Uncovering the role of the c-MYC gene translocation in cancer, led us to speculate that chromosomal translocations involving the regions carrying immunoglobulin genes could be exploited to clone unknown oncogenes involved in the pathogenesis of human lymphomas and leukemias." (PMID 40204952, 2025). "Previous studies on double/triple hit lymphoma and HGBCL with MYC rearrangement have reported cases with a few percent of TdT-positive cells, rather than being negative, due to the presence of immature B-cell features despite TdT expression below 10%." (PMID 41142614, 2025). "Standard histological examination depends on tissue availability and is currently supplemented with molecular tests, as the status of MYC, BCL2, or BCL6 gene rearrangements is required for proper lymphoma classification." (PMID 39905397, 2025). "In triple-hit lymphoma (THL), the diagnosis is confirmed with the presence of MYC alongside both BCL2 and BCL6 rearrangements." (PMID 40428800, 2025). "To avoid confounders in the outcome and biomarker analysis, we first analyzed the outcome of patients with MYC/BCL2 and/or BCL6 double-hit lymphoma (N = 7)." (PMID 40166656, 2025). "The elevated frequency of dual IGH::MYC and IGH::BCL2 fusions in the Asian group (4.9% of the cohort had HGBCL) suggests an enrichment of double-hit lymphomas, potentially contributing to the worse outcomes reported in this population." (PMID 41301875, 2025). "HALs also exhibit significantly higher expression of proliferation markers such as MYC (≥40% in 55% of cases) and BCL2 (≥50% in 65% of cases), meeting the criteria for double-expressor lymphoma (DEL) in a large proportion of cases." (PMID 40496610, 2025). "Consistent with this study, C23 showed increase toxicity in Ba/F3 murine lymphoma precursor cells exposed to 4-OHT, which promotes the nuclear translocation of a fusion between MYC and a fragment of the estrogen receptor (BaFMycER)." (PMID 39341827, 2024). "One of the two originally designated entities of high-grade B-cell lymphoma (HGBL) was one with MYC and BCL2 and/or BCL6 translocations, which was also termed double-hit (DH) or triple-hit (TH) lymphoma." (PMID 37747559, 2024). "WHO-HAEM5 separates DLBCL/HGBCL with MYC and BCL2 rearrangements from the previous entity—HGBCL with MYC and BCL2 and/or BCL6 rearrangements, also known as “double-hit”/“triple-hit” (DH/TH) lymphomas." (PMID 39518937, 2024). "Inhibition of the PIM3 kinase pathway has been shown to inhibit TNBC by indirectly targeting MYC and to enhance response to a CDK9 inhibitor in models of lymphoma." (PMID 38001268, 2024).
lymphoma (continued). "Prior to the identification of DH/TH lymphomas, FISH for MYC was performed at the pathologist’s discretion only in cases with high-grade morphology or a high ki67 proliferation index." (PMID 39684922, 2024). "Cry2 can promote ubiquitination and degradation of c-MYC, whereas deletion of Cry2 leads to enhancement of MYC-driven lymphoma in mice." (PMID 39012661, 2024). "Interestingly, both TLC-NGS and interphase FISH in this case showed increased copies of both the rearranged (3–6 copies by interphase FISH) and non-rearranged (2 copies by interphase FISH) MYC alleles, in keeping with the variable staining extensity among lymphoma cells." (PMID 38184753, 2024). "In the light of these findings, we analysed online gene expression data sets of pBL samples and compared them with other paediatric lymphomas to investigate the CD38 gene expression profile and its correlation with MYC gene expression." (PMID 39364393, 2024). "A German high-grade lymphoma study group performed a post hoc analysis of DLBCL patients, treated in prospective clinical trials, regarding their COO and expression of MYC, BCL2, and BCL6." (PMID 38397877, 2024). "In cases with morphological features intermediate between BL and DLBCL, FISH analysis for MYC, BCL2 and BCL6 rearrangements allows the correct differential diagnosis among BL, DH/TH lymphomas and HGBCL, NOS." (PMID 39684922, 2024). "Double-hit lymphomas (DHL) can be diagnosed by fluorescent in-situ hybridization (FISH), which would reveal translocations of MYC (8q24) and BCL2 (18q21) or/and BCL6 (3q27) in double-hit or triple-hit lymphomas (THL)." (PMID 39449881, 2024). "Actually, MYC can recruit EZH2 to miR-26a promoter and cooperatively repress miR-26a expression in lymphoma cells." (PMID 38561330, 2024). "The World Health Organization (WHO) classifies DLBCL with MYC and BCL2 rearrangements and the simultaneous occurrence of BCL6 gene rearrangement as double-hit lymphoma (DHL) or triple-hit lymphoma (THL)." (PMID 38381215, 2024). "High-grade B cell lymphoma (HGBL) with translocations involving MYC and BCL2 is retained as a so-called double hit (DH) lymphoma, by the 5th edition World Health Organization (WHO) classification (2022)." (PMID 38914869, 2024). "Herein, we report a case of HGBL with MYC, BCL2, BCL6, and CCND1 rearrangements, a so-called quadruple hit lymphoma and describe its molecular and cytogenetic features." (PMID 38914869, 2024). "Recently, the renewed WHO classification removed BCL-6 from the classification, leaving only rearrangements of MYC and BCL2 to define double-hit lymphomas." (PMID 38397877, 2024). "While there have been some investigations into MYC ISH expression in normal tissue and lymphoma, the data on LMO2 and the correlations described here are novel." (PMID 39001439, 2024). "In their study, the authors pointed out that CD19 is a major B Cell Receptor (BCR)-independent regulator of c-MYC levels in B cell neoplasms by activating the PI3K/AKT/GSK3 axis to promote B cell transformation and lymphoma progression." (PMID 39594704, 2024). "Immunohistochemical results of the transformed lymphomas were as follows: CD10, 24% (8/33); Bcl-6, 50% (17/34); MUM1, 65% (20/31); MYC, 30% (6/20); Bcl-2, 79% (27/34); CD5, 32% (9/28); and Ki67 ≥ 60%, 53% (18/34)." (PMID 39460552, 2024). "The differential diagnosis of BL includes HGBCL/DLBCL with MYC and BCL2 gene rearrangements (either de novo or as a transformation of a follicular lymphoma), B-lymphoblastic leukemia/lymphoma and high-grade/large B-cell lymphoma with 11q aberrations." (PMID 37530792, 2024). "The “MYC first” mechanism would be compatible with the epidemiological data and the viral clonality data, as the subsequent EBV infection will co-adjuvant to lymphoma development." (PMID 39766110, 2024). "BCL2, MYC, and/or BCL6 are simultaneously rearranged in so-called double-hit and triple-hit lymphomas, respectively." (PMID 37371852, 2023).
lymphoma (continued). "Moreover, it would be of great interest to explore if such a tool could also be used for other lymphomas, for example, the identification of MYC translocations in Burkitt lymphoma, and to establish whether such AI solutions can improve hematological cancer patients’ care." (PMID 37958379, 2023). "Nonetheless, all the peripheral blood samples in this study were acquired before 2022, and we still considered the DLBCL with MYC and BCL2 and/or BCL6 rearrangement as DHL/THL according to the 2016 World Health Organization classification of lymphoma." (PMID 36823603, 2023). "The additional Fluorescence In Situ Hybridization (FISH) analysis demonstrated MYC and BCL2 rearrangements and is consistent with high‐grade B‐cell lymphoma with MYC and BCL2 rearrangements (“double‐hit” lymphoma)." (PMID 37206289, 2023). "We engineered Ramos Burkitt’s lymphoma cell lines expressing the CT or HLH* EIF3A using the shRNA method as in HEK293T cells and observed a substantial decrease in MYC and MET protein levels in the lymphoma cells expressing the HLH* EIF3A." (PMID 37768948, 2023). "Fluorescence in situ hybridization studies for MYC and BCL2 and/or BCL6 rearrangements were performed in 27 patients, and only one patient had double‐hit lymphoma." (PMID 37997571, 2023). "Predicting MYC and BCL2 double-expressor lymphoma prognosis using the system immune-inflammatory index (SII) and prognostic nutritional index (PNI) (DEL)." (PMID 37873542, 2023). "In contrast to DLBCL/HGBL-MYC/BCL2, aggressive lymphomas with either large cell or high-grade morphology and an MYC/BCL6 double hit, but lacking BCL2 translocations, form a heterogeneous tumor category without indications of a unifying biology." (PMID 37190213, 2023). "Independent studies of the role of AID in MYC-driven lymphomagenesis in Eμ-Myc mice have produced variegated results, which could possibly be explained because the Eμ-Myc model is a model of pre-B/immature lymphoma, with mature B cell lymphomas accounting for only 19% of tumors." (PMID 37809061, 2023). "Thus, iron chelators and ironomycin may be effective treatments for MYC-driven lymphoma." (PMID 38007476, 2023). "We conclude that PRMT1 is regulated in a MYC- and mTORC1-dependent manner in BCL cells to sustain lymphoma cell proliferation and also to prevent their differentiation." (PMID 37310381, 2023). "For patients who were diagnosed with DLBCL or BL, MYC, BCL2, and BCL6 rearrangements should be detected by FISH to exclude double/triple-hit lymphoma." (PMID 37182167, 2023). "For example, Z-DNA sequences have been found to be located near translocation breakpoints in the c-MYC and BCL-2 genes, implicating them in the development of lymphomas and leukemias." (PMID 40766048, 2022). "Although patients with DH lymphomas showed inferior PFS and OS when treated with R-CHOP, the prognostic impact of MYC and BCL2 (over)expression in DLBCL in DE lymphomas and HGBL-NOS is still not clear." (PMID 35326604, 2022). "Chromosomal translocations juxtaposing the oncogenes MYC, BCL2, or BCL6 and one of the immunoglobulin loci are hallmarks in the genesis of lymphomas." (PMID 35060000, 2022). "Lymphoma material was analyzed regarding COO subtype, MYC, BCL2 and BCL6 expression (by IHC), as well as translocation status (by FISH)." (PMID 35326604, 2022). "Rapid and aggressive lymphomas develop that are characterised by CD19/B220 double positive tumour cells and the expression of high levels of both c-MYC and BCL-2, which are all markers of human DHL21." (PMID 35961968, 2022).
lymphoma (continued). "The double-hit status (simultaneous translocations of MYC and BCL2 or BCL6) was determined in 146 lymphomas, with a positive result in 11 cases (7.5%)." (PMID 34708297, 2022). "In the most aggressive forms of lymphoma, MSI2 is overexpressed and cooperates with PRMT5 in maintaining c-MYC and BCL-2, which confers resistance to PRMT5 inhibition." (PMID 36167829, 2022). "These lymphomas are known as double-hit (DH) or triple-hit (TH) lymphomas and, in the 2017 WHO classification, they belong to the provisional category of High-grade B-cell lymphomas with MYC and BCL2 or BCL6 rearrangements, or both (HGBCL-DH/TH)." (PMID 35200580, 2022). "In support of this concept, the BCL2 inhibitor venetoclax potentiated the cytotoxic activity of IACS‐010759 in MYC/BCL2 DHL cells, while the Mcl‐1 inhibitor S63845 did so in MYC‐translocated, BCL2‐negative lymphoma cell lines." (PMID 34632715, 2022). "Recently, nuclear phosphofructokinase, platelet (PFKP) was reported to stimulate CXCR4 expression through c‐MYC activity in T‐ALL and lymphoma cells." (PMID 36054080, 2022). "Consistent with heightened MYC activity, genes involved in the ATR response to replication stress were upregulated in lymphoma‐infiltrated spleens and in purified tumor cells relative to controls." (PMID 35510955, 2022). "High‐grade B‐cell lymphomas with MYC and BCL2 and/or BCL6 rearrangements were rare in the NPS, which is clinically relevant because these lymphomas have a poor prognosis." (PMID 35104916, 2022). "This project analyzed 23 cases of DLBCL, including 10 cases corresponded to single-hit lymphoma (SHL), 10 cases to double and triple-hit lymphoma (DHL/THL), and 3 cases to MYC-cluster amplification (MCAD)." (PMID 36497332, 2022). "The lymphoma cells were positive for CD79a, PAX5, CD10 (diffuse), BCL‐6, MUM1, MYC, BCL‐2, CD3 (subset) and CD5 (subset), and negative for TdT and CD61, with a proliferation index of 80%." (PMID 36467806, 2022). "The World Health Organization (WHO) classification considers cases with concurrent MYC and BCL2 and/or BCL6 rearrangement determined by fluorescence in situ hybridization (FISH) as “double-hit” lymphomas (DHL) or “triple-hit” lymphomas (THL), respectively." (PMID 35198451, 2022). "Examples include H-DNA-forming sequences in the c-MYC and BCL-2 oncogenes that co-localize with translocation hotspots in lymphomas and leukemias." (PMID 40766048, 2022). "When diffuse large B-cell lymphoma (DLBCL) has MYC rearrangement (MYC-R) and additional BCL2-R and/or BCL6-R, called double/triple-hit lymphoma (DHL/THL), the lymphoma generally has a highly adverse prognosis." (PMID 36497332, 2022). "In a study utilizing the λ-MYC mouse model of BL, tumor-promoting Tregs were found to express canonical nTregs markers Helios and NRP-1 and recognized antigens expressed by lymphoma cells." (PMID 35979372, 2022). "Initiation and formation of GCs is regulated by expression of several factors, among them MYC, B-cell lymphoma 6 (BCL6) and E2A, which are often dysregulated in GC-derived lymphomas." (PMID 36428647, 2022). "High‐grade B‐cell lymphomas with double or triple hits (MYC plus BCL2 and/or BCL6 genes rearrangements) (HGBL‐DH/TH) are usually highly aggressive lymphomas that respond poorly to conventional chemotherapeutic regimes." (PMID 35846201, 2022). "Double expressors are defined as having expression of both MYC ≥ 40% and BCL2 ≥ 50% within lymphoma cells." (PMID 35626243, 2022). "In our current probe panel for lymphoma, we targeted the BCL2, BCL6, and MYC genes, bus also included the immunoglobulin loci IGH, IGK, IGL, and other loci implicated in hematolymphoid malignancies." (PMID 34099699, 2021).